ICAM1 (intercellular adhesion molecule 1)
Diseases named in the same sentence as ICAM1 in open-access papers (continued):
Sharing a sentence is not in itself a finding about the gene and the disease.
Sepsis (continued). "mRNA expression levels of the NF-κB p65 subunit, IL-1β, and ICAM-1 were significantly increased in the aortas of mice with LPS-induced sepsis." (PMID 35328486, 2022). "IL-2R, IL-6, IL-8, IL-10, CCL-2, ICAM-1, and Urokinase were significantly higher in sepsis patients than SIRS patients." (PMID 35363162, 2022). "VCAM-1, ICAM-1, and E-selectin were reportedly upregulated in an experimental sepsis model of human umbilical vein endothelial cells." (PMID 35620579, 2022). "Studies on sepsis showed that TNF-α induced expression of ICAM-1 in endothelial cells was partially attenuated by miR-223 transferred by PMPs." (PMID 35983051, 2022). "Soluble ICAM-1 level was also augmented in sera indicating endothelial cell activation at the early stage of sepsis." (PMID 34135769, 2021). "Then, increase in ICAM-1 expression in PMN leukocytes we demonstrated 6 h after induction of sepsis probably contributed for the disease progression." (PMID 33608025, 2021). "The group of patients with pulmonary sepsis exhibited higher levels of RAGE (P = 4*10−7) and SP-D (P = 1*10−5) and lower levels of PAI-1, Ang-2 and ICAM-1 (P = 0.016, P = 1*10−6 and P = 0.036 respectively) compared to patients with extrapulmonary sepsis." (PMID 34811434, 2021). "Enhanced ICAM-1 expression was observed in cerebral microvessels of mice with sepsis compared to sham-operated mice." (PMID 33608025, 2021). "Both intercellular adhesion molecule-1 (ICAM-1) and vascular cell adhesion molecule-1 (VCAM-1) have been implicated in the migration of neutrophils during sepsis-induced ALI." (PMID 34074039, 2021). "Inflammation-triggered endothelial cells express an elevated level of ICAM-1 on their surface in the early stage of sepsis." (PMID 34135769, 2021). "Cit-AuNP treatment performed 2 h after induction of sepsis reduced ICAM-1 expression in cerebral microvessels of mice compared to saline-treated mice." (PMID 33608025, 2021). "ICAM-1 is an important inflammatory mediator, and its expression is upregulated in sepsis, which enhances inflammatory cell infiltration and organ damage." (PMID 34238972, 2021). "In sepsis, an elevated level of the circulating ICAM-1 can be utilized as a reliable biomarker that correlates with disease progression and clinical outcomes." (PMID 34135769, 2021). "Luteolin attenuates the effects of sepsis-induced ALI by suppressing the ICAM-1, iNOS pathways, oxidative stress, and NF-κB." (PMID 33532509, 2021). "After the uptake by endothelium, inflammation-induced ICAM-1 expression is reduced, which also limits leukocyte adhesion acting as a protection against excessive sepsis-related vascular inflammation." (PMID 34135769, 2021). "VLA-4 (Very Late Activation antigen 4, or CD49d/CD29) and ICAM-1 (Intercellular Adhesion Molecule 1) were assessed on lung samples obtained post mortem from 8 sepsis cases and 22 non-sepsis control cases." (PMID 33092081, 2020). "While the Tnf and Ngal genes are strongly induced in both models, Kim-1 and Tlr4 were upregulated only in ischemia–reperfusion and Icam-1 only after sepsis." (PMID 32257978, 2020). "While TNF and LCN2 are dramatically upregulated in both ischemic and septic AKI, KIM-1 is induced primarily in ischemic injury and ICAM-1 in sepsis only." (PMID 32257978, 2020). "In the present study, significantly elevated expression levels of VCAM-1 and ICAM-1 were observed in the lung tissue of mice carrying HCN of DEFA1/DEFA3 at 24 h after sepsis onset compared with those of mice with LCN of DEFA1/DEFA3 and WT mice." (PMID 30718392, 2019). "Our study will detect the potential of ICAM-1 for diagnosing the patients with sepsis and the results will be submitted to a peer-reviewed journal." (PMID 31192950, 2019). "Our study will provide the evidence of ICAM-1 in diagnosing sepsis and will be valuable for clinical decision." (PMID 31192950, 2019).
Sepsis (continued). "Considering the critical role of the inflammatory response in sepsis, we measured the effect of remifentanil on iNOS and ICAM-1 expressions in HAECs." (PMID 32082073, 2019). "ICAM-1 and iNOS are also present in elevated quantities in patients with an inflammatory state, such as sepsis." (PMID 32082073, 2019). "We will conduct the meta-analysis to evaluate the potential value of ICAM-1 for detecting the sepsis." (PMID 31192950, 2019). "In a model of polymicrobial sepsis in DREAM-deficient mice, decreased IL-6, MCP-1, and ICAM-1 release was found in bronchoalveolar lavage fluid." (PMID 29682558, 2018). "Circulating levels of soluble ICAM-1 (sICAM-1) have been associated with mortality in ICU patients, adult systemic inflammatory response syndrome (SIRS) and sepsis severity, and bacteremia." (PMID 29571293, 2018). "In summary, we demonstrated that short isoflurane exposure attenuatedneutrophil recruitment and liver injury in experimental polymicrobial sepsis modelvia Mac-1, and we suggested that fibrinogen favored Mac-1:ICAM-1 interaction byacting as a bridging molecule." (PMID 29977977, 2018). "In vivo transfection of miR-155 mimic, we found miR-155 attenuated late sepsis-mediated expression of myocardial ICAM-1 and VCAM-1." (PMID 28525390, 2017). "Together, the data support that SIRT2 regulates microvascular inflammation: low SIRT2 increases and high SIRT2 decreases leukocyte/platelet adhesion in sepsis by controlling ICAM-1 and E-selectin expression." (PMID 28503576, 2017). "There is more positive staining of ICAM and VCAM-1 in the late-septic mice myocardium compared with sham control, and miR-155 mimic transfection attenuated sepsis-mediated expression of myocardial ICAM-1 and VCAM-1." (PMID 28525390, 2017). "ICAM-1, a marker of pro-adhesive state endothelial cells, is highly expressed on endothelial cells in sepsis." (PMID 27447715, 2016). "In human sepsis, studies have shown that the higher the plasma levels of ICAM-1, the greater the number of organs damaged and the mortality." (PMID 27447715, 2016). "Similar findings of increased VCAM-1 and ICAM-1 levels have been observed in sepsis and correlate with prognosis in this condition." (PMID 27578545, 2016). "Another study which evaluated leukocyte activation in sepsis showed that cell surface expression of all activation markers (CD11b, ICAM-1, CD66b, CD63, and CD64) was increased on both neutrophils and monocytes from sepsis patients compared to healthy controls." (PMID 26063982, 2015). "The impact of β-defensin-2 on the inflammatory response (e.g., the level of ICAM-1 expression), the severity of lung injury, and the sepsis outcome (7-day survival rate) were observed and evaluated." (PMID 25210703, 2014). "Progressive increases in levels of vascular ICAM-1 occurred following sepsis, and such changes were identified in numerous organs." (PMID 25269519, 2014). "The soluble form of ICAM-1 (sICAM-1) is increased in sepsis, severe malaria, during the febrile stage of dengue infection, and in leptospirosis." (PMID 24444080, 2014). "The current study was performed to investigate the role of anti-ICAM-1 antibody in the outcome of polymicrobial sepsis and sepsis-induced immune disturbance." (PMID 24891762, 2014). "Effects were related to a blocked nitrate/nitrite level increase whereas IL-6, ICAM-1, and IL-10 were similarly induced in all sepsis groups." (PMID 26266921, 2014). "The role of anti-ICAM-1 antibody in sepsis-induced dysfunction of other organs remained to be further investigated." (PMID 24891762, 2014). "In our present study, anti-ICAM-1 antibody did attenuate sepsis-induced lung injury, as demonstrated by the histopathological test and wet-to-dry weight ratio." (PMID 24891762, 2014). "Anyway, there seemed to be more lines of evidence proving the protective role of ICAM-1 blockade in outcome of sepsis." (PMID 24891762, 2014).
Sepsis (continued). "In conclusion, our present study demonstrates that elevation of ICAM-1 in lung, thymus, and spleen is detrimental in sepsis." (PMID 24891762, 2014). "In the setting of sepsis, endothelial cells showed a marked increase in surface ICAM-1 and expression of VCAM-1 on endothelial cells." (PMID 25269519, 2014). "Intercellular adhesion molecule-1 (ICAM-1) is a key adhesion molecule mediating neutrophil migration and infiltration during sepsis." (PMID 24891762, 2014). "CLP-induced polymicrobial sepsis resulted in upregulation of ICAM-1 in different organs 24 h after CLP surgery." (PMID 24891762, 2014). "Effect of anti-ICAM-1 antibody on outcome of sepsis induced by cecal ligation and puncture (CLP) was evaluated by the survival analysis, bacterial clearance, and lung injury." (PMID 24891762, 2014). "Our present study reveals that ICAM-1 mRNA is upregulated in lung, thymus, and spleen during sepsis." (PMID 24891762, 2014). "Blockade of ICAM-1 using a specific antibody improves survival and bacterial clearance and attenuates sepsis-induced lung injury." (PMID 24891762, 2014). "Several groups have characterized signals produced by activated endothelial cells during sepsis or LPS-induced experimental endotoxic injury, including E-selectin, ICAM-1, other adhesion molecules and cytokines released from injured HUVEC cells." (PMID 23565284, 2013). "Plasma interleukin-6 and tumour necrosis factor-α concentrations were increased after acid instillation as compared to sepsis, but plasma intercellular adhesion molecule-1 concentration increased during sepsis only." (PMID 22204611, 2011). "The direct pulmonary insult (acid instillation) was associated with a greater increase in plasma IL-6 and TNF-α concentrations, but the indirect pulmonary insult (sepsis) resulted in increased plasma ICAM-1 concentrations." (PMID 22204611, 2011). "Expression of endothelial adhesion molecules such as E-selectin, VCAM-1, and ICAM-1, are a consistent feature of sepsis." (PMID 19416526, 2009). "Several mediators such as activated protein C, Caspase 1, Caspase 3, and ICAM-1 do play a pivotal role in animal models of sepsis-induced acute kidney injury." (PMID 19486524, 2009). "Plasma markers of endothelial activation (ICAM-1 and E-selectin) were both significantly raised in sepsis subjects compared with controls; however, they did not correlate with RH-PAT index." (PMID 19778457, 2009). "Despite including sepsis in the model, at the end of our analysis the only three variables that remained were log IL-8, log protein, C and log ICAM-1." (PMID 18358078, 2008). "Additionally, sepsis patients with CG/GG genotypes expressed significantly increased levels of IL-1β, IL-6, and ICAM-1 than those with CC genotype." (PMID 42311758, 2026). "Collectively, the anti-inflammatory effects of cilastatin reduced the hyperinflammatory state associated with sepsis, leading to decreased expression of endothelial adhesion molecules (VCAM-1, ICAM-1), reduced chemokine production, and lowered leukocyte infiltration in the kidney." (PMID 40869248, 2025). "This study tested the hypothesis that Kupffer cells contribute to tissue injury in sepsis via the alteration of adhesion molecules (ICAM-1 and VCAM-1) present on the endothelial cells in liver and lung tissue." (PMID 38254684, 2024). "Overall, we believe using peptides for surface modification of nanoparticles as targeting ligands to the overexpressed ICAM-1 at the inflammatory sites is a promising strategy for effective sepsis management with minimized systemic toxicities, as evidenced by these reports." (PMID 38637839, 2024). "We stained ECs after incubation with healthy and sepsis plasma to determine ICAM‐1 expression." (PMID 38981846, 2024). "The induction of sepsis resulted in increased expression of liver and lung ICAM-1 and VCAM-1." (PMID 38254684, 2024).
Sepsis (continued). "Another investigation demonstrated that platelets released microparticles (PMPs) containing functional miR-223 during sepsis can reduce the expression of ICAM-1 in endothelial cells, thereby potentially providing protection against excessive vascular inflammation induced by sepsis." (PMID 37465640, 2023). "Among other adhesion molecules, ICAM-1 is involved in the pathophysiology of sepsis." (PMID 37237555, 2023). "Adhesion molecules such as ICAM-1 facilitate inflammatory reactions that promote dysfunction and breakdown of vascular endothelia, a key pathophysiological step that precipitates organ failure in severe sepsis." (PMID 37237555, 2023). "The serum levels of soluble VCAM-1 and ICAM-1 correlate with organ dysfunction in sepsis, and these clinical observations support the hypothesis that soluble adhesion molecules are involved in the pathogenesis of sepsis." (PMID 37048076, 2023). "Rebastinib, therefore, could be a protective agent against sepsis-provoked liver injury via its influence on ICAM-1 levels." (PMID 38406786, 2023). "In sepsis, PMPs-derived miR-223 has been shown to reduce ICAM-1-Dependent Vascular Inflammation." (PMID 35983051, 2022). "Notably, there was a continuous and high ICAM-1 expression on the inner surface of the vessel in the sepsis group, and the mice in the NM group showed an intermittent and relatively low ICAM-1 expression." (PMID 35345558, 2022). "Indeed, sepsis led to increased expression of ICAM-1, VCAM-1 and P-selectin in WT mice with reduced expression of these adhesion molecules in septic CTTN KO mice comparable to sham controls." (PMID 35625756, 2022). "Due to the role of cortactin in supporting ICAM-1 functions to promote neutrophil extravasation, we hypothesised that cortactin promotes sepsis severity by supporting neutrophil influx into organs." (PMID 35625756, 2022). "In addition, the protein levels of VCAM-1 (576.3 ± 11.31 vs. 2360 ± 19.72, p < 0.05) and ICAM-1 (43.66 ± 1.69 vs. 129.2 ± 1.30, p < 0.05) were also significantly higher in the supernatant of sepsis serum group than in controls." (PMID 35145983, 2022). "In addition, the mice with RM administration also showed a significant reduction in endothelial ICAM-1 expression compared to the sepsis model mice." (PMID 35345558, 2022). "Most patients have the higher level of several cytokines and developed endothelial cell injury in the initial phase of sepsis, Urokinase, ICAM-1, and VEGFR2 may be useful to evaluate severity and prognosis of sepsis patients." (PMID 35363162, 2022). "ICAM-1 expression was measured in cerebral microvessels of mice 6 h after sepsis induction as well." (PMID 33608025, 2021). "In conclusion, septic platelets released PMPs carrying functional miR-223 lower ICAM1 expression in endothelial cells, which may be a protective role against excessive sepsis-induced vascular inflammation." (PMID 34135769, 2021). "Similarly, we observed enhanced ICAM-1 expression in cerebral blood vessels of mice 6 h after induction of sepsis." (PMID 33608025, 2021). "Enhanced ICAM-1 expression in pial vessels induced by sepsis may explain the increase in leukocyte adhesion in our model." (PMID 33608025, 2021). "TSA-pretreated mice submitted to CLP presented a protective effect during sepsis-induced lung injury, with reduced inflammatory infiltrate, decreased expression of the intercellular adhesion molecule-1 (ICAM-1) and E-selectin in lung tissue samples, and reduced plasma IL-6, with increased survival." (PMID 34322502, 2021). "Therefore, in the present study, we investigated for the first time how platelet-derived microparticles (PMPs) enriched in miR-223 modulated ICAM1 and decreased leukocyte-endothelium interaction in an in vitro model of sepsis." (PMID 34135769, 2021). "To determine whether CFH increases endothelial injury in sepsis, we measured ICAM-1, E-selectin, and PAI-1 at 24 hours in mouse plasma." (PMID 32012200, 2020).
Sepsis (continued). "Shedding of the endothelial adhesion molecules vascular adhesion molecule 1 (VCAM-1) and intercellular adhesion molecule 1 (ICAM-1) has been shown to be an important process in controlling leucocyte migration and to enhance cytokine release during sepsis in the liver." (PMID 30873161, 2019). "Therefore, our study aims to conduct a systematic review and meta-analysis to indicate the potential value of ICAM-1 for diagnosing sepsis." (PMID 31192950, 2019). "We recently demonstrated that CIRP-induced ICAM-1+ phenotype of neutrophils can promote elevated NET formation in the lungs in murine sepsis, which might suggest a link between phenotypic variation and increased NET formation during sepsis." (PMID 31000768, 2019). "The elevated TSLP level during sepsis might lead to recruitment of inflammatory cells via ICAM-1 and MIP2." (PMID 31480519, 2019). "The evidence will indicate that ICAM-1 is a valuable biomarker for detecting sepsis." (PMID 31192950, 2019). "For example, increased circulating numbers of EC and higher levels of soluble markers of EC activation/damage [e.g., intercellular adhesion molecule 1, von Willebrand factor, vascular endothelial (VE) growth factor receptor 1] correlate with more severe sepsis and higher mortality." (PMID 30116240, 2018). "In addition, increased numbers of circulating EC and soluble markers of EC damage (e.g., intercellular adhesion molecule 1, von Willebrand factor [vWF], and vascular endothelial growth factor receptor 1) correlate with more severe sepsis and higher mortality." (PMID 28250575, 2017). "In the setting of sepsis there is a sequestration of polymorphonuclear neutrophils (PMNs) at the site of infection which is modulated through the processing of various cytokines and chemokines, in particular IL-8 and ICAM-1." (PMID 27110221, 2016). "In addition, the expression of ICAM-1 (a cell surface glycoprotein) is increased on the cell surface of neutrophils allowing it to attach and migrate through the endothelium during sepsis." (PMID 27110221, 2016). "Blockade of ICAM-1 using a neutralizing antibody attenuates sepsis-induced death and lung injury." (PMID 24891762, 2014). "However, it is very strange that early and late studies showed the absolutely converse effects of ICAM-1 on the outcome of sepsis." (PMID 24891762, 2014). "Anti-ICAM-1 antibody also prevented sepsis-induced apoptosis in thymus and spleen." (PMID 24891762, 2014). "Furthermore, ICAM-1 deficient mice were less prone to septic shock than mice without any genetic manipulation which indicates the important role of ICAM-1 in conditions such as sepsis." (PMID 21352518, 2011). "Plasma ICAM-1 concentrations were higher during sepsis than after acid instillation (P = 0.031)." (PMID 22204611, 2011). "Consequently, ICAM-1 regulated via TNF-α could be a possible cause of the alteration in fenestra numbers and gap formation in LSECs, resulting in liver injury during sepsis." (PMID 38254684, 2024). "Interestingly, endothelial activation during sepsis, as indicated by high circulating levels of intercellular adhesion molecule-1 (ICAM-1), vascular cell adhesion molecule-1 (VCAM-1), E-selectin, P-selectin, and vWF, is correlated with disease severity and mortality." (PMID 37081895, 2023). "Additionally, an important role of ICAM-1+ neutrophils was recently reported in sepsis." (PMID 33608025, 2021). "Licochalcone C played a vital role in sepsis-induced inflammation through repressing NF-κB translocation and several kinds of downstream molecules, including iNOS, intercellular adhesion molecule-1 (ICAM-1), as well as vascular cell adhesion molecule-1 (VCAM-1)." (PMID 32256642, 2020). "Furthermore, soluble fragments of VCAM-1 and ICAM-1 are correlated with the severity of sepsis." (PMID 30873161, 2019). "Moreover, we reported that SIRT1 modulates the E-selectin and ICAM-1 expression during sepsis." (PMID 28503576, 2017).